LBH (LBH regulator of Wnt signaling pathway)
Diseases named in the same sentence as LBH in open-access papers (continued):
Sharing a sentence is not in itself a finding about the gene and the disease.
prostate carcinoma (3 papers, 2022 to 2023). A carcinoma that arises from epithelial cells of the prostate gland. "It has been reported that LBH, as a novel cancer‐related factor, plays crucial roles in the modulation of lung adenocarcinoma, prostate cancer, hepatocellular carcinoma and nasopharyngeal carcinoma." (PMID 34739189, 2022). "However, in agreement with our data, LBH protein is overexpressed in most prostate cancer cell lines." (PMID 37268816, 2023). "Thus, our results provide vital new insight into LBH expression and function in prostate cancer, supportive of an oncogenic role." (PMID 37268816, 2023). "Moreover, WNT was the second most enriched LBH-associated pathway in liver, pancreatic, rectal cancer; the third most enriched in esophageal (ESCA) and bladder (BLCA) cancer, and the fourth in prostate cancer (PRAD)." (PMID 37268816, 2023). "The enhancement of LBH represses the migration and proliferation in prostate cancer." (PMID 34739189, 2022). "Third, we found LBH was significantly overexpressed in prostate cancer (PRAD) in both the TCGA and Oncomine patient cohorts (>1.6-fold; p < 0.003) that together encompass more than 500 primary prostate cancers, and in prostate cancer tissues by IHC." (PMID 37268816, 2023).
leukemia (2 papers, 2023). A malignant (clonal) hematologic disorder, involving hematopoietic stem cells and characterized by the presence of primitive or atypical myeloid or lymphoid cells in the bone marrow and the blood. "We were particularly intrigued by almost equal LBH over- and under-expression in leukemia, as suggested by our Oncomine analysis." (PMID 37268816, 2023). "Interrogation of individual datasets in Oncomine and TCGA revealed that LBH was highly overexpressed in B-cell acute lymphoblastic leukemia (B-ALL, +37.7-fold), the most common and aggressive leukemia subtype, and in chronic lymphocytic leukemia (CLL, +2.8-fold)." (PMID 37268816, 2023).
Sepsis (2 papers, 2021 to 2025). Sepsis is defined as life-threatening organ dysfunction caused by a dysregulated host response to infection. "LBH alleviated lung injury in sepsis-induced ALI mouse model by inhibiting inflammation and NLRP3 inflammasome, and restrained the inflammation by inhibiting NLRP3 inflammasome in LPS-induced A549 cells, providing a novel therapeutic target for ALI." (PMID 33553423, 2021). "In this study, LBH protein expression was decreased in the lung tissues of sepsis-induced ALI mouse model." (PMID 33553423, 2021). "The Gene Expression Omnibus (GEO, accession number GSE23767) was used to analyze the differential expression of LBH in sepsis-induced ALI model." (PMID 33553423, 2021). "The present study provided in vivo and vitro evidences that LBH plays critical role in the development of sepsis-induced ALI." (PMID 33553423, 2021). "The lung W/D ratio in sepsis-induced ALI mouse model was visibly decreased by LBH overexpression (P < 0.001)." (PMID 33553423, 2021). "In summary, the protein expression of LBH was decreased in the lung tissues of sepsis-induced ALI mouse model." (PMID 33553423, 2021). "In this study, we evaluated LBH expression in sepsis-induced ALI mouse model and explored the regulatory effects of LBH on lung injury, inflammation, and NLRP3 inflammasome activation." (PMID 33553423, 2021). "Furthermore, western blot uncovered that the LBH protein expression in lung tissues was dramatically inhibited in sepsis-induced ALI mouse model (P < 0.001)." (PMID 33553423, 2021). "To sum up, we indicated that LBH overexpression may alleviate the progression of sepsis-induced ALI in vivo by inhibiting the lung injury, inflammatory responses, and NLRP3inflammasome activation." (PMID 33553423, 2021). "In vivo, overexpression of LBH decreased the lung histological changes, lung injury score, lung W/D ratio, expression of IL-1β, IL-6, and IL-18, and activation of NLRP3inflammasome in lung tissues of sepsis-induced ALI mouse model." (PMID 33553423, 2021). "Then, we further explore the biological function of LBH in sepsis-induced ALI in vivo." (PMID 33553423, 2021). "LBH overexpression could markedly reduce the lung injury score in sepsis-induced ALI mouse model (P < 0.01)." (PMID 33553423, 2021). "The mRNA and protein expression of LBH was decreased in sepsis-induced ALI." (PMID 33553423, 2021). "LBH overexpression reduced the lung injury score, lung W/D ratio, expression of proinflammatory cytokines, and NLRP3 inflammasome activation in sepsis-induced ALI mouse model." (PMID 33553423, 2021). "Third, the regulatory relationship between LBH and NLRP3 inflammasome on inflammatory responses in sepsis-induced ALI is limited to the cellular level and in vivo experiments are needed." (PMID 33553423, 2021). "LBH overexpression could markedly downregulate the expression of NLRP3 and ASC in lung tissues of sepsis-induced ALI mouse model (P < 0.001)." (PMID 33553423, 2021). "First, there are many other downstream signaling pathways of LBH that have not yet been determined in sepsis-induced ALI." (PMID 33553423, 2021). "Upregulation of LBH could significantly reduce the NLRP3 and ASC protein expression in lung tissues of sepsis-induced ALI mouse model (P < 0.001)." (PMID 33553423, 2021). "In this study, overexpression of LBH reduced the lung histological changes, lung injury score, and lung W/D ratio in sepsis-induced ALI mouse model, indicating that LBH may act as a protective gene for treating sepsis-induced ALI in vivo." (PMID 33553423, 2021). "In this study, LBH overexpression decreased the expression of proinflammatory cytokines and NLRP3 inflammasome components in lung tissues of sepsis-induced ALI mouse model, indicating that LBH treatment attenuated the inflammation and NLRP3inflammasome activation in sepsis-induced ALI mice." (PMID 33553423, 2021).
acute myeloid leukemia (1 paper, 2023). Acute myeloid leukemia (AML) is a group of neoplasms arising from precursor cells committed to the myeloid cell-line differentiation. "In contrast, LBH was underexpressed in more indolent, late-onset acute myeloid leukemia (LAML/AML, −1.1-fold in TCGA; −2.5-fold in Oncomine), and in slow-growing, chronic myeloid leukemia (CML, −2.47) and chronic adult T-cell leukemia/lymphoma (ATLL, −2.27)." (PMID 37268816, 2023).
Arthritis (1 paper, 2018). Inflammation of a joint. "A recent study demonstrating that LBH deficiency exacerbates arthritis in an in vivo model supports these findings." (PMID 29554943, 2018).
breast tumors (1 paper, 2015). "Among the 1070 breast tumors, 682 (64 %) were Luminal A (LA), 166 (16 %) were Luminal B HER2 negative (LBH−), 47 (4 %) were Luminal B HER2 positive (LBH+), 108 (10 %) were triple negative (TN) and 67 (6 %) were HER2-enriched tumors (H2+)." (PMID 26405647, 2015).
diffuse large B-cell lymphoma (1 paper, 2023). "While LBH was overexpressed in aggressive pediatric leukemia (i.e., B-ALL), and in the most common lymphoma subtype, Diffuse large B-cell lymphoma, correlating with reduced patient survival, it was under-expressed in late-onset adult leukemia/lymphomas, and in myeloma." (PMID 37268816, 2023).
endometrial carcinoma (1 paper, 2023). A malignant tumor arising from the epithelium that lines the cavity of the uterine body. "In contrast, we identified LBH underexpression in melanoma, ovarian, cervical, and uterine-endometrial cancers, where it was associated with good prognosis, suggestive of tumor suppressive roles." (PMID 37268816, 2023).
head & neck cancer (1 paper, 2023). "Importantly, we newly identified aberrant LBH overexpression in pancreatic, esophageal, colon, rectal, bladder, kidney, prostate, testicular, head & neck cancers, and in sarcoma." (PMID 37268816, 2023). "LBH was overexpressed in most cancers compared to normal tissues (>1.5-fold; p < 0.05), including colon-rectal, pancreatic, esophageal, liver, stomach, bladder, kidney, prostate, testicular, brain, head & neck cancers, and sarcoma, correlating with poor prognosis." (PMID 37268816, 2023). "Second, LBH has first been shown to have tumor suppressive activity in cell line models of nasopharyngeal cancer (NPC), a rare head and neck cancer arising from nose-throat epithelium." (PMID 37268816, 2023). "In contrast, our meta-analysis shows consistent LBH overexpression, correlating with reduced patient survival, in head and neck squamous cell carcinoma (HNSC), the most common head and neck cancer type originating from mucous epithelium of the oral cavity, pharynx, and larynx." (PMID 37268816, 2023).
invasive breast carcinoma (1 paper, 2023). A carcinoma that infiltrates the breast parenchyma. "Lastly, LBH was underexpressed in invasive breast carcinoma (BRCA, −1.4 to 2.5-fold), although two datasets in Oncomine also reported LBH overexpression, consistent with our previous results." (PMID 37268816, 2023). "First, both Oncomine and TCGA whole patient cohorts show downregulation of LBH mRNA in invasive breast cancers (BRCA) compared to normal breast tissue, seemingly in contradiction with its reported oncogenic roles in breast carcinogenesis." (PMID 37268816, 2023).
kidney cancer (1 paper, 2023). Primary or metastatic malignant neoplasm involving the kidney. "Notably, in colon, stomach, and kidney cancer, WNT was the top enriched pathway among LBH-coexpressed genes, consistent with LBH being a direct WNT/β-catenin target gene." (PMID 37268816, 2023).
melanoma (1 paper, 2023). A malignant, usually aggressive tumor composed of atypical, neoplastic melanocytes. "The cancer types showing LBH downregulation were lung, melanoma, ovarian, cervical, and uterine cancer, while both LBH over- and under-expression were observed in hematopoietic malignancies." (PMID 37268816, 2023).
non-Hodgkin lymphoma (1 paper, 2023). Distinct from Hodgkin lymphoma both morphologically and biologically, non-Hodgkin lymphoma (NHL) is characterized by the absence of Reed-Sternberg cells, can occur at any age, and usually presents as a localized or generalized lymphadenopathy associated with fever and weight loss. "Conversely, LBH immunostaining was significantly decreased in solid cancers of the lung (LUSC), skin (SKCM), ovaries (OV), and in non-Hodgkin’s lymphoma." (PMID 37268816, 2023).
ovarian carcinoma (1 paper, 2022). A malignant neoplasm originating from the surface ovarian epithelium. "In the present study, we found that LBH contributed to the malignant progression of ovarian cancer both in vitro and in vivo." (PMID 34739189, 2022).
pancreatic cancer (1 paper, 2023). "Heatmap analysis in colorectal, stomach, and pancreas cancer patient datasets showed a consistent overlap between LBH overexpression and WNT signaling genes associated with pathway activation, i.e., WNT2, WNT5A, WNT11, LEF1, TCF4 or TCF7, CCTNB1, CCND1, JUN, DKK3." (PMID 37268816, 2023). "Notably, LBH-WNT-Integrin co-expression gene signatures showed high significance in predicting poor survival in patients with colorectal, stomach, esophageal, and pancreatic cancer." (PMID 37268816, 2023).
Parkinson disease (1 paper, 2023). A progressive degenerative disorder of the central nervous system characterized by loss of dopamine producing neurons in the substantia nigra and the presence of Lewy bodies in the substantia nigra and locus coeruleus. "Nonetheless, individual pathway analysis showed that in LUAD, the top five pathways inversely correlated with LBH expression were the ubiquitin-proteasome pathway (14%), de novo purine and/or pyrimidine biosynthesis (13% and 8%, respectively), DNA replication (13%), and Parkinson disease (10%)." (PMID 37268816, 2023).
pulmonary fibrosis (1 paper, 2022). Chronic progressive interstitial lung disorder characterized by the replacement of the lung tissue by connective tissue, leading to progressive dyspnea, respiratory failure, or right heart failure. "Five genes demonstrated concordant directions of effects between the ILA [IPF transcripts] and IPF scores (CXCR6, IL7R, LBH, LRRC39, PLBD1), suggesting these genes may represent important biologic processes in promoting the progression of pulmonary fibrosis." (PMID 35715807, 2022). "Thus, there is already evidence that IL7R, LBH, and CXCR6 are important for understanding processes that promote pulmonary fibrosis, and LRRC39 and PLBD1 are additional targets for future studies." (PMID 35715807, 2022).
skin cancer (1 paper, 2023). "We also analyzed the pathways associated with LBH underexpression in lung and skin cancer." (PMID 37268816, 2023).
thyroid cancer (1 paper, 2023). "In agreement with our meta-analysis, LBH protein was significantly overexpressed in cancers of the gastrointestinal tract (i.e., PAAD, ESCA, COAD, READ, LIHC, STAD), the urogenital system (i.e., KIRC, PRAD, TGCT), and in head and neck (HNSC) and thyroid cancer compared to normal tissues." (PMID 37268816, 2023).
uveitis (1 paper, 2025). An inflammatory process affecting a part of or the entire uvea. "Furthermore, there was a significant correlation between patients’ age-specific regulation of genes MYLIP and PDE4A in the uveitis only group and CCR7, LBH, and LCK in the systemic disease-associated uveitis group." (PMID 40270958, 2025).
tumor (13 papers, 2004 to 2023). "In contrast, the high expression of DYNC1I1, FAM83D, and LBH, have been previously associated with poor prognosis and an aggressive tumor phenotype in GC." (PMID 37772256, 2023). "Given that DNA methylation is a key epigenetic mechanism affecting gene regulation and tumor development, we next analyzed association between LBH expression and methylation status in TCGA datasets." (PMID 37268816, 2023). "High intra-tumoral LBH expression in these cancers was significantly associated with reduced patient survival, and/or advanced tumor grade, implying novel oncogenic LBH functions." (PMID 37268816, 2023). "To assess if dysregulation of LBH correlated with tumor progression, we examined the association of LBH expression with tumor stage in cancer-specific TCGA datasets." (PMID 37268816, 2023). "For LBH+ tumors poorer DMFS was associated with tumor size (>20 mm) [HR = 4.2 (1.3–13.7), P = 0.02], vascular invasion [HR = 5.7 (1.6–20.9), P = 0.008] and Claudin-low phenotype [HR = 6.6 (1.6–27.2), P = 0.009]." (PMID 26405647, 2015). "Therefore, the results from this study indicate that LBH may activate a range of cancer-associated pathways and lead to tumor proliferation and invasion phenotypes." (PMID 31119084, 2019). "Validation of the clinical association of LBH with WNT activation in gastrointestinal cancer cell lines, and in colorectal patient samples by IHC uncovered that LBH is specifically expressed in tumor cells with nuclear beta-catenin at the invasive front." (PMID 37268816, 2023). "Limb-Bud and Heart (LBH) is a developmental transcription co-factor deregulated in cancer, with reported oncogenic and tumor suppressive effects." (PMID 37268816, 2023). "Future studies are needed to dissect the precise role of LBH in WNT-Integrin-mediated tumor cell invasion." (PMID 37268816, 2023). "Our data showed that the depletion of LBH remarkably attenuated tumor growth of U251 cells in vivo, as demonstrated by tumor size, tumor volume and tumor weight, as well as the decreased expression of Ki‐67." (PMID 34739189, 2022). "The reversed correlation in expression between MIR31HG and LBH in the various cells and tumor cohorts, along with the reversed phenotypes found between MIR31HG and LBH, suggest a cause-effect situation." (PMID 34445087, 2021). "Exogenous LBH expression decreases tumor cell invasiveness, while knockdown of LBH reverses the oncogenic suppression present in MIR31HG deletion subclones." (PMID 34445087, 2021). "Upregulation of LBH mRNA in GC was also confirmed by comparison of paired tumors and adjacent non-tumor tissues in GSE29272 (N = 134, P < 0.001)." (PMID 31119084, 2019). "In multivariable analysis, factors associated with shorter DMFS varied according to molecular subtype, with tumor size being associated with shorter DMFS in the LBH−, LBH+ and TN groups and the Rho GEF Trio and BCL2 phenotypes in TN tumors only." (PMID 26405647, 2015). "For LBH+ tumors, large tumor size (20 mm), vascular invasion and Claudin-low phenotype were associated with poorer DMFS." (PMID 26405647, 2015). "Importantly, IHC validation in colorectal patient samples revealed that LBH is specifically expressed in tumor cells with WNT signaling activity at the invasive front which engage directly with extracellular matrix to invade adjacent tissue." (PMID 37268816, 2023). "To determine whether the observed changes in LBH mRNA expression in the different tumor types translated into similar changes in LBH protein, we performed multiorgan tissue microarray analysis (TMA), using an LBH antibody validated for IHC." (PMID 37268816, 2023). "Importantly, staining of adjacent tumor sections with antibodies to β-catenin revealed that LBH was expressed in a subset of invasive CRC cells with nuclear β-catenin expression, which is a hallmark of WNT activation." (PMID 37268816, 2023).